TNF (tumor necrosis factor)
Diseases named in the same sentence as TNF in open-access papers (continued):
Sharing a sentence is not in itself a finding about the gene and the disease.
SAPHO syndrome (24 papers, 2009 to 2026). SAPHO syndrome (acronym for Synovitis, Acne, Pustulosis, Hyperostosis and Osteitis) is an auto-inflammatory disease, mainly characterized by the association of neutrophilic cutaneous involvement and chronic osteomyelitis. "Additionally, multiple inflammatory factors, including Tumor Necrosis Factor (TNF)-α, Interleukin (IL)-1β, IL-8, IL-17, and IL-18, have been implicated in SAPHO syndrome pathogenesis, contributing to the complexity of treatment." (PMID 40709177, 2025). "For SAPHO syndrome, TNF-α inhibitors have been reported as the most effective biologics agents, while IL-1 and IL-17/IL-23 inhibitors are considered second-line treatments." (PMID 40404944, 2025). "Previous studies have shown that proinflammatory cytokines—such as TNF-α, interleukin (IL)-1β, IL-6, and IL-8—are strongly expressed in patients with SAPHO syndrome, promoting an amplified inflammatory response." (PMID 41303152, 2025). "TNF-α inhibitors are the most widely used biologics in the treatment of SAPHO syndrome, showing benefits for both cutaneous and osteoarticular manifestations." (PMID 40709177, 2025). "Bone and cartilage biopsy specimens from patients with SAPHO syndrome exhibit increased TNF-α production and expression." (PMID 40342407, 2025). "These dual actions on immune and bone cells underscore TNF-α’s pivotal role in the pathogenesis and progression of SAPHO syndrome, contributing to both inflammation and bone pathology." (PMID 39286247, 2024). "Specifically, IL-8 has been shown to upregulate the production of TNF-α and IL-1β, creating a feedback loop that amplifies the inflammatory response, which is crucial for sustaining chronic inflammation characteristic of SAPHO syndrome." (PMID 39286247, 2024). "In SAPHO syndrome, tumor necrosis factor α (TNF-α) serves as a key pro-inflammatory cytokine, significantly influencing inflammatory responses and bone remodeling." (PMID 39286247, 2024). "An overproduction of IL-1β and dysregulation of IL-8, IL-17, IL-18, and TNF-α has been identified in SAPHO syndrome." (PMID 38984133, 2024). "For instance, neutrophils in patients with SAPHO syndrome demonstrate excessive activation, releasing substantial quantities of pro-inflammatory cytokines like IL-8 and TNF-α." (PMID 39286247, 2024). "Common step 2–3 treatments were pamidronate, methotrexate, and TNF-a-inhibition (anti-TNFα), the latter two regarded especially convenient to co-target extra-skeletal inflammation in SAPHO syndrome." (PMID 37480122, 2023). "It was reported that 17% of SAPHO syndrome patients treated with TNF-α antagonists developed secondary paradoxical psoriatic lesions, and three patients showed aggravated palmoplantar pustules." (PMID 36983699, 2023). "In recent years, biologics have been increasingly used for the treatment of SAPHO syndrome, with TNF-α antagonists being the most used." (PMID 35984163, 2022). "It has been well established that patients with SAPHO syndrome have elevated levels of TNF-alpha from purified neutrophils as well as in bone biopsies analyzed with in situ hybridization and immunohistochemistry." (PMID 33655144, 2018). "Upadacitinib may represent a promising treatment option for difficult-to-treat SAPHO syndrome, particularly in cases with inadequate response to TNF-α inhibition." (PMID 42079610, 2026). "Nevertheless, some patients might still develop severe rashes during treatment with TNF-α inhibitors, which led physicians to select appropriate therapeutic options to treat SAPHO syndrome." (PMID 40709177, 2025). "Furthermore, the signaling pathways involving IL-1 and TNF-α are central to the pathophysiology of SAPHO syndrome, supporting the use of biologic treatments such as TNF-α inhibitors and IL-1 receptor antagonists." (PMID 39286247, 2024).
SAPHO syndrome (continued). "In SAPHO syndrome, IL-10’s regulatory function potentially alleviates chronic inflammation and autoimmune responses by reducing the production of pro-inflammatory cytokines such as tumor necrosis factor α (TNF-α) and interleukin-1β (IL-1β)." (PMID 39286247, 2024). "SAPHO syndrome is a chronic autoimmune disease that is manifested by raised levels of different inflammatory cytokines and neutrophil stimulation; among these changes, the upregulation of TNF-alpha, interleukin (IL)-8, IL-17, and IL-1b was recorded." (PMID 39233977, 2024). "This article reviews the cytokines involved in the pathogenesis of SAPHO syndrome, such as tumor necrosis factor α (TNF-α), interleukin 1β (IL-1β), IL-6, IL-10, and transforming growth factor-β (TGF-β), and discusses their potential as intervention points for treatment." (PMID 39286247, 2024). "TNF blockers, such as etanercept, adalimumab, and infliximab are generally used in patients with CRMO and SAPHO syndrome after methotrexate failure with good results." (PMID 38984133, 2024). "In axSpA, elevated levels of ESR and tumor necrosis factor (TNF) are frequently observed; however, we found that ESR was elevated in some patients with axial SAPHO syndrome (66.7%), but TNF was not increased." (PMID 41303152, 2025).
Sciatica (24 papers, 2009 to 2025). Pain in the lower back and hip radiating in the distribution of the sciatic nerve. "Seventeen key cytokines, chemokines and matrix metalloproteinases (MMPs) implicated in sciatica pathogenesis including TNFα and IL-6, were assayed in duplicate using commercial multiplex detection kits and measured using a Luminex suspension array system." (PMID 31077179, 2019). "Treatment with a neutralizing antibody for TNF-α was shown to produce a marked improvement in leg pain and a reduction in the number of patients with disc herniation-associated sciatica." (PMID 30585203, 2018). "Clinical reports suggest that anti-TNF-α drugs, such as etanercept and infliximab, have the potential to relieve neuropathic pain caused by sciatica or disc herniation." (PMID 24642694, 2014). "Tumor necrosis factor-alpha (TNF-α) is an inflammatory factor involved in the pathophysiological mechanism underlying disk herniation-induced sciatica." (PMID 25050851, 2014). "The currently available evidence demonstrated that other than reducing the RR of discectomy or radicular block (combined endpoint) at medium-term follow-up, TNF-α inhibitors showed limited clinical value in the treatment of sciatica caused by herniated discs and/or spinal stenosis." (PMID 25050851, 2014). "The serum concentrations of IL-6 and TNF-α are closely related to the severity of pain and functional impairment in sciatica." (PMID 41424922, 2025). "Previous observational studies have reported associations between elevated levels of certain inflammatory markers like TNF-α, IL-6, and IL-8 in the serum or cerebrospinal fluid of sciatica patients compared to healthy controls." (PMID 39015317, 2024). "The results of this study are in contrast to those of Wang who found elevated levels of TNFα and IL-6 in patients with severe sciatica (defined as pain level of > 3 on VAS)." (PMID 31077179, 2019). "The objective of this study is to assess the value of tumor necrosis factor (TNF)-α inhibitors in the treatment of sciatica." (PMID 25050851, 2014). "A newly published systematic review and meta-analysis revealed that the evidence supporting the use of TNF-α inhibitors to treat sciatica is inadequate." (PMID 25050851, 2014). "We now know that removing TNF-α from the picture will not abolish neuropathic pain as has already been demonstrated by the failure of TNF-α antagonists in clinical trials for sciatica." (PMID 20398373, 2010). "Partly for this reason, glucocorticoids and, more recently, TNFα inhibitors were introduced in the treatment of sciatica." (PMID 19906289, 2009). "However, a comprehensive examination and meta‐analysis revealed that the existing data were inadequate to endorse the utilization of anti‐TNF agents in individuals suffering from sciatica." (PMID 40787071, 2025). "Multiple clinical trials have also demonstrated the efficacy of IL‐6 receptor inhibitors like tocilizumab, and TNF inhibitors including adalimumab, etanercept, and infliximab in alleviating pain among individuals diagnosed with lumbosacral radiculopathy and sciatica." (PMID 40787071, 2025). "We speculate that in the early-stages of sciatica, the accumulation of neutrophils and other immune cells released inflammatory mediators like IL-6, TNF-α, and CCL-2 at the injury site." (PMID 41424922, 2025). "Furthermore, serum cytokines, including tumor necrosis factor-α (TNF-α) and interleukin 8 (IL-8), have been found to be higher in patients with sciatica than in healthy controls." (PMID 35061744, 2022). "Previous studies have reported serum inflammatory biomarkers of sciatica, and these include TNF-α, IL-4, IL-6, IL-8, IL-10, IL-17, IL-21, T helper lymphocytes 17, phospholipase A2, C-reactive protein, C-X3-C motif ligand 1, C-C motif ligand 2 and mast cell proteinase-1." (PMID 33535986, 2021). "IL-1β, IL-10, TNF-α, and IL-17 have been detected in human patients with sciatica and could be considered potential serum, biopsy, or cerebrospinal fluid biomarkers." (PMID 33183347, 2020).
Sciatica (continued). "Interestingly, the use of anti-TNF-alpha treatment, including adalimumab, has been previously proposed for the treatment of severe acute sciatica, a typical neuropathic pain condition." (PMID 33333779, 2020). "In the past decade, some scholars have attempted to use TNF-α inhibitors to treat sciatica." (PMID 25050851, 2014). "The use of glucocorticoids and TNF inhibitors in the treatment of sciatica might therefore hinder DH resorption and, possibly, the median or long-term evolution of the disease." (PMID 19906289, 2009). "Moreover, a study showed that the upgraded expression of TNF in serum was associated with poor recovery in patients with LBP plus sciatica or not." (PMID 36918849, 2023). "However, it has been suggested that there may be pro-inflammatory cytokine activation in herniated lumbar discs, and anti-TNF has been used successfully to treat disc herniation-induced sciatica." (PMID 27764105, 2016). "Through the analysis of multiple signaling pathways, we elucidated the involvement of various signaling pathways (such as the Cytokine-cytokine receptor interaction, Chemokine, TNF, NOD-like receptor, and NF-kappa B signaling pathways) in the progression of early sciatica." (PMID 41424922, 2025). "For patients with disc herniation and sciatica, the levels of TNF-α in their CSF and serum have also not been found to be significantly increased." (PMID 35061744, 2022). "Subsequent randomized controlled trials failed to support the benefits of systemic anti-TNF-α treatment, but a recent report did show positive benefits of epidurally administered etanercept in the treatment of sciatica." (PMID 20398373, 2010).
scleroderma (24 papers, 2011 to 2026). Scleroderma is a rare autoimmune connective tissue disorder characterized by abnormal hardening of the skin and, sometimes, other organs. "One of the key players in the inflammation and fibrosis branches of the SSc pathogenesis triad, TNF-α, contributes to fibroblast activation and its expression has also been linked to the progression and severity of scleroderma." (PMID 41614927, 2026). "TNF-α has also been implicated in the pathogenesis of scleroderma." (PMID 39337619, 2024). "That treatment with MTX is sufficient to control disease activity in many patients also suggests that TNF-α likely plays a role in the pathogenesis of scleroderma." (PMID 39337619, 2024). "IL-6, IL-13, IL-17, and TNF-α are cytokines recognized to be involved in the pathophysiology of scleroderma." (PMID 34445632, 2021). "Nimbolide attenuated the progression of scleroderma by controlling inflammatory factors such as TNF-α, IL-1β, and p-NF-κB and by downregulating the TGF-β/Smad signaling axis (inhibition of TGF-β expression and Smad2/3 protein phosphorylation)." (PMID 34258301, 2021). "Th17 cells and pro-inflammatory cytokines such as IL-1β, IL-6, IL-17, and TNF-α play important roles in the pathogenesis of scleroderma." (PMID 33947424, 2021). "BLM-induced scleroderma mice exhibited increased serum levels of TNF-α and INF-γ, and WKYMVm treatment alleviated the BLM-induced increase of TNF-α and INF-γ." (PMID 31552041, 2019). "Furthermore, EchA treatment markedly attenuated serum levels of inflammatory cytokines, such as tumor necrosis factor-α and interferon-γ, in a murine scleroderma model." (PMID 33922418, 2021). "In this study, we showed that BLM-induced scleroderma stimulated infiltration of CD68-positive macrophages into scleroderma skin, and the serum levels of the inflammatory cytokines, TNF-α and INF-γ, were up-regulated in the scleroderma model; however, WKYMVm treatment attenuated these effects." (PMID 31552041, 2019). "Similarly, this modification can be induced in healthy skin fibroblasts by TNF-α, and RelA-P-Ser536 myofibroblast-like positive cells are localized in fibrotic areas in scleroderma patients." (PMID 22996371, 2013). "The soluble form of adhesion molecules related to the function of the TNF-alpha signaling pathway and the serum PGRN level showed a significant positive correlation with the QT interval of the surface-ECG in the scleroderma group." (PMID 39000486, 2024). "EchA co-treatment markedly attenuated the BLM-induced increase in TNF-α and IFN-γ levels, suggesting that EchA administration reduces systemic inflammation in BLM-induced scleroderma." (PMID 33922418, 2021). "Consistently, out of 45 patients under biologic treatment, of who more than half were receiving anti-TNF agents (25/45), 39 had symptomatic infection, none were severe, but one scleroderma patient who was receiving tocilizumab was hospitalized in our study." (PMID 35456195, 2022). "In addition, we evaluated the relevant infoammatory cytokines of IL1, IL6, IL12,TNFα, and CXCL12 in the normal, scleroderma and treatment groups, respectively." (PMID 35315234, 2022). "Excessive apoptosis, which cannot be treated by macrophages, may induce proinflammatory cytokines such as tumor necrosis factor-α (TNF-α) or interferons (IFNs), and play a triggering role in the pathogenesis of bleomycin-induced scleroderma." (PMID 22028717, 2011). "Moreover, studies in a scleroderma model demonstrate stimulation of B cells with the ECM component hyaluronan activates TLR2 and TLR4 and results in inflammatory cytokine secretion, including IL-6, TNFα, and IFNγ." (PMID 34381449, 2021). "Moreover, WKYMVm treatment reduced the serum levels of inflammatory cytokines, such as tumor necrosis factor-α, and interferon-γ, in the scleroderma model of wild-type mice but not in Fpr2 knockout mice." (PMID 31552041, 2019).
scleroderma (continued). "The WKYMVm-induced reduction of TNF-α and INF-γ levels was observed in the serum of BLM-induced scleroderma model of wild type mice, but not in Fpr2 knockout mice." (PMID 31552041, 2019).
spinal cord injury (24 papers, 2010 to 2024). Penetrating and non-penetrating injuries to the spinal cord resulting from traumatic external forces (e.g., WOUNDS, GUNSHOT; WHIPLASH INJURIES; etc.). "Previous studies indicated that in spinal cord injuries, M1 macrophages facilitate phagocytosis and secrete pro-inflammatory cytokines such as interleukin-6 (IL-6) and tumor necrosis factor alpha (TNF-α)." (PMID 38668224, 2024). "In a previous study, rats with spinal cord injuries received (DP) therapy, which markedly decreased their levels of TNF-α and IL-6 activity." (PMID 36641447, 2023). "Studies have found that miR-223 and the inflammatory factors TNF-α, IL-1β, and IL-6 were highly expressed in the lesions of acute spinal cord injury in mice, which reached the maximum peak at 12–24 h after injury." (PMID 32295141, 2020). "Recently, increased HDAC3 and TNFα and decreased miRNA-130a expression has been observed in PBMCs from patients with spinal cord injuries." (PMID 27904654, 2016). "Meanwhile, pro-inflammatory cytokine production (such as TNF-α and IL-1β) and iNOS expression were significantly decreased after administration of oleuropein aglycone in spinal cord trauma." (PMID 24842137, 2014). "For instance, it has been found that electroacupuncture reduced the proportion of M1 macrophages and the levels of TNF-α, IL-1 β, and IL-6 in rats with spinal cord injury and also increased the amount of IL-10 and M2 macrophages and upregulated the expression of the M2 markers CD206 and NT-3." (PMID 33727948, 2021). "The levels of cytokines CXCL5, CCL11, CXCL11, IL10, TNFα, and MIF were different between patients with baseline American Spinal Injury Association Impairment Scale (AIS) grades of A or B, whilst IL2 (>2 fold) and MIP-3a (>6 fold) were significantly expressed in the cervical and thoracic regions." (PMID 33806460, 2021). "Another study demonstrated that Tan IIA could reduce the levels of IL-6, TNF-α and IL-1β by markedly inhibiting the activation of NF-κB and the mitogen-activated protein kinases (MAPKs) pathways in a spinal cord injury model." (PMID 25157742, 2014). "TNF and its receptors, TNFR1 and TNFR2, are increased rapidly after spinal cord injury (SCI) and high TNF concentrations have been linked to more severe SCI and worse functional outcomes." (PMID 37372129, 2023). "Inhibiting the expression and activation of both metal matrix proteinase (MMP)-2 and MMP-9 after spinal cord injury (SCI) and the mRNA expressions of TNF-α, IL-1β, COX-2, and iNOS." (PMID 27951737, 2017). "For instance, an animal model of spinal cord injury (SCI), EA has shown neuroprotective effects by reducing levels of microglial and proinflammatory mediators, such as precursor pro-nerve growth factor and proinflammatory cytokines (TNF-α, IL-1β, and IL-6)." (PMID 32283868, 2020). "Finally, a decrease in TNF-α levels two hours after the wheelchair half marathon was noted in the cervical spinal cord injury group but not in the spinal cord injury group." (PMID 37372810, 2023).